TH (tyrosine hydroxylase)
Diseases named in the same sentence as TH in open-access papers (continued):
Sharing a sentence is not in itself a finding about the gene and the disease.
Lewy body disease (4 papers, 2015 to 2025). "Because striatal degeneration without measurable loss of TH-positive nigral neurons is a feature of incipient Lewy body disease and early PD, we decided to use our model as a tool to study gene expression changes in the ventral midbrain leading up to the degeneration in the dorsal striatum." (PMID 32997293, 2021). "This study also included samples from incidental Lewy body disease (ILBD) cases, since ILBD is considered a non-symptomatic precursor to PD, with subjects having significant loss of tyrosine hydroxylase-producing neurons." (PMID 26834537, 2015).
morphine dependence (4 papers, 2012 to 2022). Strong dependence, both physiological and emotional, upon morphine. "Sinomenine administration can prevent the morphine-induced increase in the expression of TH and NR2B, suggesting that sinomenine appropriately inhibits morphine dependence by enhancing the signaling function mediated by TH and NR2B." (PMID 36188580, 2022). "Consistent with the immunohistochemistry results, the relative level of TH in the VTA decreased with prolonged morphine dependence." (PMID 30634592, 2019). "The results of the present study indicated that the expression of TH, Nurr1, and Pitx3 significantly decreased and damage to dopaminergic neurons was clearly visible after prolonged morphine dependence." (PMID 30634592, 2019). "Altogether, these results suggest that an up-regulation of TH would facilitate the capacity of noradrenergic neurons to synthesize NA, which could contribute to the increase in NA turnover and in the hemodynamic changes observed in the heart during morphine dependence." (PMID 24409147, 2013).
myopia (4 papers, 2015 to 2024). "Nevertheless, the current finding of a putative decline in retinal TH expression is consistent with previous indications that such an effect is associated with myopia development." (PMID 26495845, 2015). "It has been demonstrated that the retinal dopamine level is lower in different myopia animal models, is accompanied by a low dopamine biosynthesis rate and is associated with reduced tyrosine hydroxylase activity (TH), this being the rate-limiting enzyme in dopamine biosynthesis." (PMID 25922643, 2015). "Such a role is indicated for DA since retinal DA levels and TH activity declined in eyes deprived of sharp vision by using either diffusers (form deprivation myopia, FDM) or minus lenses (lens induced myopia, LIM)." (PMID 26495845, 2015).
vitamin D deficiency (4 papers, 2018 to 2025). A nutritional condition produced by a deficiency of VITAMIN D in the diet, insufficient production of vitamin D in the skin, inadequate absorption of vitamin D from the diet, or abnormal conversion of vitamin D to its bioactive metabolites. "Animal studies demonstrate that vitamin D deficiency is associated with dysfunctional development of dopaminergic neurons, possibly through reduced expression of tyrosine hydroxylase, the rate-limiting enzyme in dopamine synthesis." (PMID 40497025, 2025). "In fetal mice, vitamin D deficiency caused suppression of neural forkhead box protein P2(FoxP2) and tyrosine hydroxylase (TH), especially in females." (PMID 30410834, 2018). "There is a robust decrease in TH level in mice brain with reduced staining of TH proteins in substantia nigra which shows a strong relation between vitamin D deficiency and dopamine dysfunction." (PMID 30410834, 2018). "Vitamin D deficiency decreases the expression of tyrosine hydroxylase (TH) and nuclear receptor-related 1 protein (Nurr1), which plays a key role in the maintenance of the dopaminergic system of the brain, in the rodent hippocampus." (PMID 29562608, 2018).
amyloid (3 papers, 2024). "We report extensive and widespread TH+ fiber loss, along with limited loss of TH+ in neurons in association with amyloidosis." (PMID 39696597, 2024). "Findings using amyloid-only rodent models of AD indicate a DA-dependent decrease in memory formation and reward processing, concomitant with a decrease in TH+ cell bodies in the VTA and DA release in the NAc2." (PMID 39516200, 2024).
anemia (3 papers, 2021 to 2025). A reduction in the number of red blood cells, the amount of hemoglobin, and/or the volume of packed red blood cells. "Anemia was also associated with RLS given the important role of iron as a cofactor for tyrosine hydroxylase, which converts tyrosine to L-DOPA, a dopamine precursor." (PMID 34597340, 2021). "The profound anemia and hemolysis are explained by a genomic arsenal encoding multiple hemolysins (ahh1, hlyA, hly-III, TH)." (PMID 41154733, 2025).
Arrhythmia (3 papers, 2013 to 2021). Any cardiac rhythm other than the normal sinus rhythm. "Moreover, we observed significantly elevated expression of TH proteins and mRNAs in the infarcted border zone, while TH-positive nerve fibers were disordered, indicating that sympathetic remodeling increases the susceptibility to arrhythmia after MI." (PMID 34221073, 2021). "In addition, present finding suggest that the activation of TH could be a factor that would contribute to cardiovascular alteration, such as arrhythmias, observed in heroin addicts and could be useful for future treatment strategies focused on addictive processes." (PMID 24409147, 2013).
Ataxia (3 papers, 2012 to 2025). Ataxia refers to impaired coordination of voluntary muscle movement. "Severe: progressive postural instability, gait and limb ataxia, weight loss, premature death, neuronal intranuclear inclusions, decreased TH-positive neurons in the substantia nigra." (PMID 33071748, 2020).
Cocaine addiction (3 papers, 2016 to 2025). "TH rs10770141 modulates subjective effects of cocaine in participants with cocaine dependence." (PMID 40671874, 2025).
COVID-19 (3 papers, 2024 to 2025). A disease caused by infection with severe acute respiratory syndrome coronavirus 2. "The density of NM-containing and TH-immunoreactive neurons was decreased in COVID-19 and PD(D) brain donors compared with age-matched controls (NM+: −58%, p = 0.008% and −71%, p < 0.001, respectively; TH+: −44%, p = 0.035; −64%, p < 0.002)." (PMID 38237586, 2024). "Furthermore, we observed reduced numbers of neuromelanin+ and tyrosine-hydroxylase (TH)+ DA neurons and fibers in a cohort of severe COVID-19 patients." (PMID 38237586, 2024).
deafness (3 papers, 2015 to 2021). An inherited or acquired condition characterized by the complete loss of the ability to hear from one or both ears. "The use of inherited disease genes sequencing panel identified the causative and novel variants in deafness related genes (GJB2, MYO7A, CDH23, TH and EVC2) in deaf brothers." (PMID 30881389, 2019). "It is concluded that in addition to novel mutations in MYO7A, TH and EVC2, the CDH23 and GJB2 can also be responsible for deafness in the family with consanguineous marriages." (PMID 30881389, 2019). "Described for both the CN and the IC, are deafness (cochlear ablation) induced temporal changes in gene expression for TH, DA receptors and genes related to AANs." (PMID 26257610, 2015). "In the current study, deafness related gene expression levels and co-localization of TH with markers for GABA, glycine, and glutamate are examined in the CN and IC to determine likely AAN candidates for the neuromodulatory actions of DA." (PMID 26257610, 2015). "Following 2 months of deafness the general density of TH labeling changes, with less labeling in the neuropil and more labeling in boutons and fibers of passage." (PMID 26257610, 2015). "Following deafness TH labeling decreases throughout the IC, but VGLUT3 immunolabeling shows no change." (PMID 26257610, 2015). "Of the AAN related genes, only two genes showed deafness related changes with a similar time course as TH, GLYT2, and GABAtp." (PMID 26257610, 2015). "Changes in the gene expression of TH were compared with changes in the gene expression of markers for AANs in the cochlear nucleus (CN) and inferior colliculus (IC) to determine whether those deafness related changes occur concurrently." (PMID 26257610, 2015). "Depending upon the IC subdivision examined, deafness related decreases in TH production (not dopamine beta hydroxylase (DBH) or phenylethanolamine-N-methyl transferase (PNMT)) can be either transient (days to weeks) or long lasting, i.e., months." (PMID 26257610, 2015). "However, localization of TH labeling does not appear to change following deafness, but the labeling (intensity and number of elements) is decreased." (PMID 26257610, 2015). "Co-localization and/or possible contact between TH and GLYT2 was noted and did not seem affected by deafness." (PMID 26257610, 2015).
gastric cancer (3 papers, 2021 to 2024). A primary or metastatic malignant neoplasm involving the stomach. "For the analysis of the sympathetic nervous system in gastric cancer, we analyzed both the nerve fibers in the tumor tissues and the extra-tumoral nerve fibers by evaluating the percentage of tyrosine hydroxylase in each nerve fiber." (PMID 38541693, 2024). "For example, cancer stem cells of gastric cancer and colorectal cancer can differentiate into sympathetic neurons producing tyrosine hydroxylase (TH) and parasympathetic neurons producing vesicular Ach transporter." (PMID 36900158, 2023). "Subsequently, NE synthetase enzymes tyrosine hydroxylase (TH), dopa decarboxylase (DDC), and dopamine-β-hydroxylase (DBH), degrading enzymes monoamine oxidase A and B (MAOA and MAOB), and catechol-O-methyl transferase (COMT) were analyzed in TCGA database of gastric cancer." (PMID 33855088, 2021).
glioma (3 papers, 2023). A benign or malignant brain and spinal cord tumor that arises from glial cells (astrocytes, oligodendrocytes, ependymal cells). "In this study, we revealed that DRD2/ERK/β-catenin pathway and Dopamine/ERK/TH regulatory loop jointly mediate the promoting effect of chronic stress on glioma malignant progression." (PMID 37415171, 2023). "In RASF, TNF might enhance catecholamine synthesis not only by increasing TH expression but also by increasing cofactors important for the activity of TH such as tetrahydrobiopterin (BH4) as demonstrated in glioma cells." (PMID 36918850, 2023).
heart failure (3 papers, 2022 to 2024). Inability of the heart to pump blood at an adequate rate to meet tissue metabolic requirements. "First, Nox2 deficiency reduces myocardial oxidative stress, attenuates decreased catecholaminergic histofluorescence profiles, and restores protein expression levels of PGP9.5, GAP43, tyrosine hydroxylase and NET in doxorubicin-induced heart failure." (PMID 38521855, 2024).
hyperthyroidism (3 papers, 2017 to 2022). Overactivity of the thyroid gland resulting in overproduction of thyroid hormone and increased metabolic rate. "Therefore, if clinicians encounter patients with hyperthyroidism symptoms with elevated free TH but normal TSH levels and negative thyroid antibody, they should ruminate on the syndrome of inappropriate secretion of TSH (SITSH)." (PMID 36619586, 2022).
ischemic stroke (3 papers, 2017 to 2024). A stroke disorder caused by obstruction of blood flow to the brain, due to thrombotic (local blood clot formation) or embolic (due to a blood clot or other material traveling from another site) event. "This study aimed to investigate the potential protective role of lentiviral GNDF delivery on the small population of tyrosine hydroxylase (TH) positive dopamine producing striatal neurons after ischemic stroke." (PMID 34773698, 2022). "In the present study, we found that the expression and enzymatic activity of TH were significantly reduced in a rat model of ischemic stroke." (PMID 29245933, 2017).
nicotine addiction (3 papers, 2015 to 2025). "TH is the rate-limiting enzyme of DA synthesis and its increased expression is an important factor in nicotine addiction." (PMID 29690521, 2018). "The TLR4 signal is also activated in the ventral tegmental area (VTA), where it upregulates the expression of tyrosine hydroxylase (TH), the rate-limiting enzyme of dopamine (DA) synthesis, which modulates locomotor activity and reward and is an important factor in nicotine addiction." (PMID 29690521, 2018). "Increased TH expression and dopamine release are important factors in nicotine addiction." (PMID 26169054, 2015). "The TH promoter contains canonical and non-canonical CRE motifs that bind CREB and modulate expression, and it is the rate-limiting enzyme for DA synthesis, an important factor in nicotine addiction." (PMID 29690521, 2018).
Ovarian cyst (3 papers, 2018 to 2022). The presence of one or more cysts of the ovary. "In the senescent rats, the TH-positive neurons (arrow) around the ovarian cysts were lower in contrast to the neurons in the OS (arrows)." (PMID 35217964, 2022).
restless legs syndrome (3 papers, 2009 to 2024). A condition that occurs while resting or lying in bed; it is characterized by an irresistible urgency to move the legs to obtain relief from a strange and uncomfortable sensation in the legs. "The second exercise increased PTPRD (protein tyrosine phosphatase receptor delta-type) protein levels, decreased tyrosine hydroxylase (TH) protein levels, and improved sleep parameters in both cycles of restless leg syndrome." (PMID 38714990, 2024). "Antipsychotic-induced restless legs syndrome was linked to polymorphisms located on CLOCK, BTBD9, GNB3, and TH genes, clozapine-induced somnolence was correlated with polymorphisms of HNMT gene, while insomnia was associated with variants of the MTNR1 gene." (PMID 29587340, 2018).
Segawa syndrome (3 papers, 2010 to 2024). "We speculated that mutation in the TH gene may clinically manifest by affecting the production of dopamine and catecholamine downstream, which enriches the gene pool of Segawa syndrome." (PMID 36568392, 2022). "Second, when NPB and Segawa syndrome are highly suspected, screening for tyrosine hydroxylase (TH) and sphingomyelin phosphodiesterase-1 (SMPD1) gene mutations is critical to determine an accurate diagnosis." (PMID 38826802, 2024). "We collected venous blood from four patients with Segawa syndrome and their parents for real-time quantitative polymerase chain reaction analysis of TH gene expression." (PMID 36568392, 2022).
sudden infant death syndrome (3 papers, 2016 to 2023). Unexpected death in infancy which remains unexplained following autopsy, review of the medical history, and investigation of the death circumstances and death scene. "Sudden infant death syndrome victims were reported to show reduced immunoreactivity for tyrosine hydroxylase in the dorsal vagal nucleus and ventrolateral reticular formation in the medulla oblongata." (PMID 27445960, 2016).
tauopathy (3 papers, 2016 to 2025). Neurodegenerative disorders involving deposition of abnormal tau protein isoforms (tau proteins) in neurons and glial cells in the brain. "On the other side, Nmnat1 overexpression reduces early behavioral impairment in a mouse model of tauopathy and reverses the loss of tyrosine hydroxylase (TH) neurons in the nigrostriatal pathway of the 3xTgAD mice." (PMID 35401143, 2022). "Thus, it has been shown that NURR1 is significantly decreased in the PD nigral neurons containing αS-immunoreactive inclusions and in the DA nigral neurons with neurofibrillary tangles, correlating with the loss of TH and diminished intracellular pathology in both αSNP and tauopathies." (PMID 40422188, 2025). "Tauopathy increased also the gene expression of TH in the LC." (PMID 26792515, 2016). "We suggest that similarly to LC, increased TH expression in the A1 noradrenergic cell group might represent a compensatory response to impairment of TH-positive A1 neurons in this transgenic (SHR72) animal model of tauopathy." (PMID 26792515, 2016).
thyroid (3 papers, 2018 to 2023). "In addition, acetochlor was found to elicit different responses in the secretion of THs, TH-linked crucial gene expression, and binding affinity to TRs that resulted in thyroid disruption, thus affecting the growth of zebrafish larvae." (PMID 37637141, 2023).
toxoplasmosis (3 papers, 2020 to 2022). A parasitic disease contracted by the ingestion or fetal transmission of toxoplasma gondii. "The results of another study indicated that the overexpression of encoding genes of tyrosine hydroxylase (AaaH1 and AaaH2) in Toxoplasma parasite leads to an increase in dopamine production in infected mouse with toxoplasmosis." (PMID 35530748, 2022). "The authors of a study in 2009 believed that tyrosine level in infected animal models with toxoplasmosis decreased at two days after parasite injection due to the presence and expression of the encoding genes of tyrosine hydroxylase (AaaH1 and AaaH2) in Toxoplasma parasite." (PMID 34447590, 2021).
Tremor (3 papers, 2015 to 2022). An unintentional, oscillating to-and-fro muscle movement about a joint axis. "As the SN is the neuronal region where the enzyme tyrosine hydroxylase (TH) is most abundant, TH deficiency has shown to be associated with hypokinetic-rigid symptoms while other features like tremor are largely absent in patients with TH deficiency." (PMID 35854141, 2022).
vitiligo (3 papers, 2013 to 2024). Generalized well circumscribed patches of leukoderma that are generally distributed over symmetric body locations and is due to autoimmune destruction of melanocytes. "Complement-fixing melanocyte autoantibodies and antibodies against transcription factors SOX-9, SOX-10, and AADC and tyrosine hydroxylase (TH) strongly correlate with the presence of vitiligo and alopecia." (PMID 24167503, 2013). "Additionally, as compared to healthy volunteers, a high proportion of patients with AA and vitiligo is positive for autoantibodies against tyrosine hydroxylase, and those autoantibodies from AA and vitiligo patients recognize identical epitopes, suggesting the similarity between AA and vitiligo." (PMID 38673994, 2024).
-dependence (2 papers, 2014 to 2019). "In this study, we examined the effects of pre- and post-treatment with AJN on striatal DAT, D2R, and TH levels in a rat model of morphine-dependence." (PMID 25134609, 2014). "However, it remains unclear what effects TH, Nurr1, and Pitx3 have on dopaminergic neurons relating to morphine dependence." (PMID 30634592, 2019). "Immunohistochemistry showed that the number of TH+, Nurr1+, and Pitx3+ cells, and the number of TH+ cells expressing Nurr1 or Pitx3, significantly decreased in the VTA after a long period of morphine dependence." (PMID 30634592, 2019).
Alcohol (2 papers, 2016 to 2025). "The data suggest that TLR4 signaling in VTA dopaminergic neurons controls impulsivity related to the regulation of TH expression, likely contributing to the initiation of alcohol drinking and its transition to alcohol dependence." (PMID 27187237, 2016).
breast tumors (2 papers, 2021 to 2023). "Immunofluorescence of Neurofilament Light Chain (NF-L, neural fibers), Tyrosine Hydroxylase (TH, catecholamine nerves) and synaptophysin (SYP) confirm the presence of neural signals in both human and mouse breast tumors." (PMID 37463926, 2023). "Notably, proximity analyses between neural markers and nuclear phospho-CREB1/ATF1 indicate that higher cancer-cell CRE activity is present in the region proximal to neural signals (NF-L, TH and SYP positive area) in breast tumors." (PMID 37463926, 2023).
cardiac hypertrophy (2 papers, 2018 to 2023). "Ang II increased blood pressure, myocardial hypertrophy, fibrosis, inflammatory infiltrates and tyrosine hydroxylase expression, as compared to the control group." (PMID 37445888, 2023). "Empagliflozin administration prevented the development of myocardial hypertrophy, fibrosis, inflammatory infiltrates and tyrosine hydroxylase overexpression in Ang II-treated rats, without affecting blood glucose and the Ang II-dependent increase in blood pressure." (PMID 37445888, 2023).